SNORD7 (small nucleolar RNA, C/D box 7)
Synonyms: Z30; mgU6-47
Gene: Small nucleolar RNA gene on chromosome 17 (35,573,657 to 35,573,753, forward strand). Ensembl gene ENSG00000207297.
Gene Ontology:
Biological process: RNA processing
Cellular component: nucleolus
Homologues: Orthologues: macaque SNORD7 (96% identical), guinea pig SNORD7 (95% identical), pig SNORD7 (91% identical), rabbit SNORD7 (91% identical), mouse Snord7 (87% identical), rat Snord7 (87% identical).
Diseases named in the same sentence as SNORD7 in open-access papers:
SNORD7 is named in the same sentence as 1 disease in open-access papers, as found by Europe PMC text mining. Sharing a sentence is not in itself a finding about the gene and the disease.
SNORD7 shares sentences with these, for which no sentence is quoted: benign tumour (1 paper).